PON3 (paraoxonase 3)
Diseases named in the same sentence as PON3 in open-access papers (continued):
Sharing a sentence is not in itself a finding about the gene and the disease.
cancer (18 papers, 2012 to 2025). A tumor composed of atypical neoplastic, often pleomorphic cells that invade other tissues. "PON-3 overexpression reduces cytochrome c release and cardiolipin peroxidation, leds to loss in mitochondrial integrity, enhancing cell death resistance in cancers cells by regulating c- MAPK signaling pathway." (PMID 31052559, 2019). "In this work, we identified that PON3 is associated with the multi-drug resistance of EC cancer." (PMID 30386177, 2018). "PON3 is overexpressed in a variety of human cancers and has been shown to eliminate mitochondrial superoxide production, resulting in antioxidant and anti‐apoptotic benefits, saving tumor cells from death." (PMID 39641443, 2024). "PON3 is overexpressed in a variety of human cancer types and is shown to abrogate mitochondrial superoxide production, consequently granting anti-oxidative and anti-apoptotic benefits, allowing tumor cells to escape death." (PMID 35326240, 2022). "There is an emerging interest regarding the role of PON2 and PON3 in cancer due to their remarkable upregulation in some tumor tissues." (PMID 35326240, 2022). "While studies have shown that PON3′s expression serves to inhibit cell proliferation through interference in cell cycle progression, invasion, and migration in certain cancers, it has also been shown to display oncogenic properties." (PMID 35326240, 2022). "An interesting phenomenon is that both PON2 and PON3 are upregulated in the early stages and some subtypes of cancer, whereas they are downregulated in the late stages." (PMID 33562328, 2021). "The authors also reported that overexpressed PON3 in the cancer cell lines diminished the intramitochondrial formation of superoxide anions, suggesting a direct interaction with the Q10 coenzyme." (PMID 34679639, 2021). "Promoter hypermethylation of PON3 and/or decreased mRNA expression has been reported in several types of cancers, including OC." (PMID 34567062, 2021). "Oxidative stress and chronic inflammation are closely linked to cell death and cancer, therefore it appears conceivable that tumors take advantage of the antioxidative function of PON2/PON3 to escape cell death." (PMID 33562328, 2021). "PON1 and PON3 are involved in the lipoxygenase pathway, leading to the generation of eicosanoids impacting cancer development, progression and immune responses." (PMID 34439311, 2021). "Despite the extensive studies of PON3 in cancer cells, the roles of PON3 in EC are rarely evaluated, especially the involvement in drug resistance." (PMID 30386177, 2018). "It has been reported that PON2 and PON3 are upregulated in various cancer tissues including ovarian cancer." (PMID 29531225, 2018). "In accordance with previous studies, we identified that the promoter region of PON3 is hypermethylated in EC cancer." (PMID 30386177, 2018). "In cancer, PON2 and PON3′s association is based on their up-regulated expressions in various tumors with anti-apoptotic and protective effects in the mitochondria from several chemical-mediated dysfunctions." (PMID 28467805, 2017). "Schweikertet al. reported PON3 was upregulated in several types of cancer tissues, which appear to contradict to its protective role observed in other inflammatory disorders." (PMID 27661119, 2016). "In the following section, we give an overview of studies that assessed expression of PON1, PON2, or PON3 in various cancers, with the majority of studies seemingly reporting a deregulation of these proteins." (PMID 22666600, 2012). "Using the same cDNA arrays as for PON2, our group showed a considerably increased PON3 expression in all tested cancer types, except cervix." (PMID 22666600, 2012). "A tumor subtype and stage-specific analysis revealed that both PON2 and PON3 are upregulated rather in the early stages and some subtypes of cancer, whereas the expression in the late stages of the tumor seems to be declining." (PMID 22666600, 2012).
cancer (continued). "We will focus on the role of PON2 and PON3 in cancer based on recent discoveries on the mechanism of action of these proteins in proliferation and apoptosis." (PMID 22666600, 2012). "Studies have shown that PON3 may serve as a double-edged sword when it comes to cancer as it is downregulated in some cancer types, but the antioxidant effect of PON3 helps to inhibit normal apoptotic mechanisms in others." (PMID 35326240, 2022). "The contrast in the findings suggest that PON3 may serve as a double-edged sword in disease progression due to differences in regulation of its enzymatic function as an antioxidant in various cancer pathways." (PMID 35326240, 2022). "In recent years, overexpression of PON2 and PON3 has been observed in cancer cells and it has been proposed that both enzymes may be involved in tumor survival and resistance to stress." (PMID 31052559, 2019). "Moreover, PON3 expression is remarkably up-regulated in a variety of human cells, including cancer cells." (PMID 30386177, 2018). "PON3 gene has a high expression level in cancer tissues of the lung, liver and colon." (PMID 30386177, 2018). "A total of three differentially hypermethylated genes (CCNE1, PON3, and CCNDBP1) and two differentially hypomethylated genes (DDX43 and CHL1) were selected for the validation based on their β-value and association with CRC as well as other cancers." (PMID 28243201, 2017). "PON3 gene has high expression in cancer tissues of the lung, liver and colon." (PMID 28243201, 2017). "One reason for the high expression level of PON3 in cancer tissue is certainly the low basal expression level of PON3 in healthy tissues but may nevertheless suggest a role for PON3 in cell death escape." (PMID 22666600, 2012). "However, there are various other such analyses, which showed altered expression of PON3 (up as well as downregulated) in different types of cancers." (PMID 22666600, 2012). "Thus, the current review focuses on PON3 and summarizes the PON substrates, specific activities, kinetic parameters, and their association with cardiovascular as well as other diseases such as HIV and cancer." (PMID 35326240, 2022). "In the current review, we focus on PON3 including its substrate specificity as well recent findings on the role of PON3 in cardiovascular diseases and other disease states such as HIV and cancer." (PMID 35326240, 2022). "This suggests that the determination of standardized PON1, PON3, and MDA levels may be a useful biomarker in predicting recurrence following cancer surgery." (PMID 32549522, 2020). "Thus, if a cancer cell needs to escape from mitochondrial redox-dependent cell death, it appears beneficial to increase PON2 or PON3 expression." (PMID 22666600, 2012).
tumor (14 papers, 2012 to 2025). "In this same study, in vivo findings demonstrated that PON3 inhibited tumor growth and drug resistance." (PMID 35326240, 2022). "In the present study, PON1, MDA, and PON3 enzyme activities were investigated one month after surgical tumor excision." (PMID 32549522, 2020). "To investigate the in vivo effect of PON3 on EC drug resistance, we generated a K510-derived tumor model in nude mice." (PMID 30386177, 2018). "Upon transfection of si-PON3, K510-derived tumors were approximately 2.4-folds heavier than the control cells, suggesting that PON3 inhibits tumor growth in vivo." (PMID 30386177, 2018). "In the qRT-PCR cohort including 135 pairs of HCC and the adjacent non-tumor tissues, PON3 was markedly downregulated in HCC tissues of most patients (86.67%)." (PMID 27661119, 2016). "The ability of PON3 to restore the sensitivity of PON2-deficient tumor cells to C12 suggests that overlapping enzymatic activities of PON2 and PON3 mediate C12 killing activities." (PMID 26758417, 2016). "Tumors with PON3 overexpression (HCC-LM3-PON3) showed a significantly decreased tumor growth compared with its control (HCC-LM3-NC), reflected by tumors' volume and weight (p = 0.046 for tumor volume, p = 0.021 for tumor weight)." (PMID 27661119, 2016). "Number of tumor colonies formed at day 14 was much more in PON3 knockdown cells and markedly reduced in PON3 overexpression cells." (PMID 27661119, 2016). "Subsequently, we found that silencing PON3 by specific shRNA accelerated tumor growth in vivo, whereas PON3 over-expression led to a remarkable suppression of tumor growth." (PMID 27661119, 2016). "Western-blot results showed that PON3 protein level was also downregulated in HCC when compared with the adjacent non-tumor liver tissues." (PMID 27661119, 2016). "In the same way, xenograft tumor formation in nude mice was also assessed using cells with exogenous PON3 overexpression and their respective controls." (PMID 27661119, 2016). "PON3 expression level negatively correlates with tumor size and number, suggesting that PON3 expression may inhibit HCC cell proliferation." (PMID 35326240, 2022). "In addition, in vivo EC-derived tumor xenografts in nude mice were generated to test the effect of PON3 on the chemoresistance of EC cells." (PMID 30386177, 2018). "All these findings made us to propose that PON3 might be a tumor suppressor, considering its high methylation in the promoter region and low expression level in multiple cancers." (PMID 30386177, 2018). "Furthermore, the tumor weight for the si-PON3/DDP K510 mice was heavier than that in the DDP K510 mice." (PMID 30386177, 2018). "In vivo experiments also found that PON3 inhibits tumor growth in nude mice." (PMID 30386177, 2018). "In contrast, our findings suggested the tumor-suppressive function of PON3 in HCC." (PMID 27661119, 2016). "PON3 downregulation was found in HCC in the present study and its expression was negatively associated with several progressive clinicopathological features, including tumor size." (PMID 27661119, 2016). "Our results showed that knockdown of PON3 evidently promoted tumor growth." (PMID 27661119, 2016). "Intriguingly, PON2 as well as PON3 are frequently found upregulated in tumor samples." (PMID 22666600, 2012). "In addition to its antioxidant effect, PON3 may also have an anti-apoptotic effect, which may be related to the physiology and pathology of tumor cells." (PMID 34567062, 2021). "Since PON3 possesses overlapping enzymatic activities with PON2 to cleave C12, we investigated whether PON3 could functionally compensate for the loss of PON2 and re-sensitize tumor cells to C12." (PMID 26758417, 2016). "Further confirmation of the PON3 role in the DDP resistance of EC came from the immunohistological analysis of PON3 and Ki67 (an indicator of tumor cell proliferation) in the tumor sections of the DDP-treated versus PBS-treated mice." (PMID 30386177, 2018).
tumor (continued). "Finally, the evaluation of methylation in ctDNA via ddPCR, such as the detection of RASSF1A or paraoxonase 3 (PON3), may suggest the state of the disease and survival outcomes in CM patients, even in the absence of tumor mutation data for BRAF, RAS or EGFR genes." (PMID 35887633, 2022). "This could indicate that, especially in the early stages of tumor formation, the antioxidative and antiapoptotic function of PON2 and PON3 is important and beneficial as it helps generating the platform for malignant transformation." (PMID 22666600, 2012). "The negative relation of PON3 and tumor size had been proved above, implying that PON3 may inhibit HCC cells proliferation." (PMID 27661119, 2016). "Similarly, gender, Edmondson grade, tumor size, TNM stage, serum AFP, and PON3 expression level could be predictor for OS." (PMID 27661119, 2016). "In addition, we determined a prognostic signature with potential clinical applicability and validated PON3 DNA methylation and OVOL1 protein expression as biomarkers with prognostic information independent of tumor thickness and ulceration." (PMID 28578692, 2017).
cardiovascular disease (6 papers, 2012 to 2024). "Another aspect of note is the paucity of information on the relationships between PON2 and PON3 gene polymorphisms and enzymatic activities vs. cardiovascular disease." (PMID 25405733, 2014). "Elevated serum PON3 levels were also observed in patients with HIV-1, a condition associated with macrophage activation, cardiovascular disease, and direct upregulation of T-cell activation in vitro, a hallmark of this infectious disease." (PMID 39456469, 2024).
neurodegenerative disease (4 papers, 2021 to 2025). A disorder of the central nervous system characterized by gradual and progressive loss of neural tissue and neurologic function. "Altogether, PON3 could play an important role both in the CSF and in certain brain areas in the pathogenesis of neurodegenerative diseases such as AD, and more research in the near future will hopefully be pursued in this highly unexplored PON3 field." (PMID 33505588, 2021). "However, we accounted for several potential confounding factors (e.g., age, gender, etc.)known to be associated with PON1, PON3, and neurodegenerative diseases, and the significant results observed were independent of these factors." (PMID 39456469, 2024).
bacterial infection (2 papers, 2012 to 2020). "For example, three lactonases are present in humans: PON1, PON2 and PON3; of these, only PON2 is expressed in all tissues, and it appears to be involved in the first step of defense against bacterial infection." (PMID 32993120, 2020).
infection (2 papers, 2012 to 2020). The state of being infected such as from the introduction of a foreign agent such as serum, vaccine, antigenic substance or organism. "Infection and inflammation leads to increased LDL oxidation and higher LDL oxidation has previously been shown to be associated with ME/CFS Increased levels of PON3 may be a mechanism to compensate for increased oxidative stress caused by increased inflammatory mediators in the blood." (PMID 32692761, 2020).
neurological diseases (2 papers, 2023 to 2025). "After observing that PON-3 protein circulates to other regions such as the brain, researchers have studied the association between neurological diseases and PON-3 expression." (PMID 37108044, 2023). "In this review we summarize some of the key studies establishing the links between PON-3 and neurological disorders, but more research is clearly needed to gain insight into these associations." (PMID 37108044, 2023).
PON3 also shares sentences with these, for which no sentence is quoted: peripheral artery disease (3 papers); cervical carcinoma (2); clear cell sarcomas of the kidney (2); depression (2); lung adenocarcinoma (2); papillary thyroid carcinoma (2); Sepsis (2); type 1 diabetes (2); acute liver failure (1); adenoma (1); allergic disease (1); benign breast tumor (1); bladder cancer (1); Cerebral ischemia (1); cerebrovascular disease (1); chronic hepatitis (1); Crohn disease (1); cutaneous melanoma (1); deafness (1); dyslipidemia (1); endometrial cancer (1); heart disease (1); infectious disease (1); Infertility (1); inflammatory bowel disease (1); iron deficiency (1); kidney disease (1); lupus erythematosus (1); metabolic disease (1); metabolic dysfunction-associated steatotic liver disease (1).
A further 8 diseases each share a sentence with PON3 in 1 paper.